ARF1 (ARF GTPase 1)
Diseases named in the same sentence as ARF1 in open-access papers (continued):
Sharing a sentence is not in itself a finding about the gene and the disease.
colorectal cancer (5 papers, 2020 to 2025). A primary or metastatic malignant neoplasm that affects the colon or rectum. "To investigate the mechanism of anti‐tumor immunity induced by Arf1‐ablation in cancer (stem) cells, we adopted short hairpin RNAs to knock down Arf1 in CT26 colorectal cancer cells and co‐cultured them with DC2.4 dendritic cells." (PMID 37786300, 2023). "In order to directly prove that the cytoplasm DNAs in DCs came from the Arf1‐ablated tumor cells, we co‐cultured mouse DCs with human DLD1 colorectal cancer cells that were transfected with either shScramble or shArf1." (PMID 37786300, 2023). "In colorectal cancer, phosphatase of regenerating liver 3 (PRL-3) interacts with Arf1 to promote cell migration." (PMID 31991585, 2020).
glioma (5 papers, 2019 to 2022). A benign or malignant brain and spinal cord tumor that arises from glial cells (astrocytes, oligodendrocytes, ependymal cells). "In glioma stem cells, circRNA ARF1 is transcriptionally regulated by U2AF2 and circRNF121 in osteoarthritis is regulated by LEF1." (PMID 36072902, 2022). "Recently, a potential role for Arf1 in glioblastoma progression was suggested, and over-expression of Arf6 was shown to enhance glioma cell migration both in vitro and in vivo." (PMID 30909495, 2019). "For instance, circRNA ARF1 expression in glioma stem cells is regulated by U2AF2." (PMID 35832649, 2022). "In glioma tissues and cells, miR-342-3p is regulated by circ_ARF1, forming a feedback loop composed of U2AF2, ARF1, ISL2, and miR-342-3p, which modulates glioma development." (PMID 36120594, 2022).
head and neck squamous cell carcinoma (5 papers, 2019 to 2025). A squamous cell carcinoma that arises from any of the following anatomic sites: lip and oral cavity, nasal cavity, paranasal sinuses, pharynx, larynx, and salivary glands. "Most recently, we showed for the first time that active GTP-bound Arf1 is much higher in metastatic head and neck squamous cell carcinoma (HNSCC) cells compared with their paired non-metastatic cells, supporting the critical role of Arf1 activation in HNSCC metastasis." (PMID 30884855, 2019).
melanoma (5 papers, 2015 to 2025). A malignant, usually aggressive tumor composed of atypical, neoplastic melanocytes. "The new Arf1 inhibitors and PD-1 blockade synergistically and effectively reduced and eliminated tumors in melanoma grafts." (PMID 39872623, 2023).
ovarian carcinoma (5 papers, 2018 to 2022). A malignant neoplasm originating from the surface ovarian epithelium. "Finally, ARF1 is upregulated in ovarian tumors, when compared with adjacent non-cancerous tissues and its overexpression is associated with ovarian cancer cell proliferation and migration through the PhosphoInositide 3-Kinase (PI3K) pathway." (PMID 32426352, 2020). "The ARF1 mediated-activation of the PI3K signaling cascade promotes the G0/G1 to S phase transition of epithelial ovarian cancer cells and, in turn, the cell proliferation." (PMID 35805075, 2022). "Recent evidence shows that ARF1 stimulates epithelial ovarian cancer cell migration by interacting with PI3K and activating its signaling cascade." (PMID 35805075, 2022). "ARF1 plays a central role in maintaining the structure and function of the Golgi apparatus and is highly expressed in breast, prostate and ovarian cancers." (PMID 32426352, 2020). "Additionally, ARF1 expression level is related to the grade of ovarian cancer, and its overexpression proliferation and migration of ovarian cancer cells." (PMID 33345740, 2021).
periventricular nodular heterotopia (5 papers, 2016 to 2025). "Concerning the roles of Arfs in cortical development, mutations in human genes for ARF1 and its GEF, ARFGEF2, have been linked to periventricular nodular heterotopia, suggesting the involvement of Arf1 in cortical radial migration." (PMID 37848288, 2023). "In addition to the patient with p.Y35H, a second unrelated individual with periventricular heterotopia with a de novo, rare missense variant in ARF1, c.379A>G (p.K127E) was also found." (PMID 28868155, 2016).
amyotrophic lateral sclerosis (4 papers, 2021 to 2025). Amyotrophic lateral sclerosis (ALS) is a neurodegenerative disease characterized by progressive muscular paralysis reflecting degeneration of motor neurons in the primary motor cortex, corticospinal tracts, brainstem and spinal cord. "The recent work has highlighted the utility of a neuron‐specific Arf1‐knockout mouse model and corresponding cells for elucidating the nexus between lipid metabolism disorders and amyotrophic lateral sclerosis (ALS) and multiple sclerosis (MS)." (PMID 40019378, 2025). "A gene mutated in amyotrophic lateral sclerosis (ALS) and frontal temporal degeneration (FTD), called C9orf72, was recently identified as a GAP for ARF1." (PMID 34368129, 2021). "Finally, we show that the Arf1-reduction-induced neuroimmune-IFN-γ-gliosis pathway exists in human NDs, particularly in amyotrophic lateral sclerosis and multiple sclerosis." (PMID 38239560, 2023).
glioblastoma (4 papers, 2019 to 2024). The most malignant astrocytic tumor (WHO grade IV). "AGAP2 with regulatory activity on Arf1 and Arf5 enhances cancer cell survival, migration, and invasion in glioblastoma." (PMID 37182141, 2023). "It was reported that ARF1 gene promoter methylation is associated with EGFR gene amplification and can promote the distinct tumor infiltration in glioblastoma." (PMID 32894165, 2020).
invasive breast carcinoma (4 papers, 2015 to 2020). A carcinoma that infiltrates the breast parenchyma. "Furthermore, regulation of Rac1 signaling by ARF1 which directly interact with miR-96 in the regulatory network is associated with invasive breast cancer cells." (PMID 25874214, 2015). "Recent studies reported that GRB2 acts as an adaptor protein which plays a central role in the regulation of ARF1 and ARF6 activation in invasive breast cancer." (PMID 32595697, 2020).
lung carcinoma (4 papers, 2023 to 2026). "PAQR11 maintains a compact and polarized Golgi structure in lung cancer cells that have undergone epithelial-mesenchymal transition and recruits ARF1 to the Golgi membrane to facilitate vesicle formation and secretion." (PMID 38662435, 2024). "Upregulation of Arf1, Arf4, and Arf6 were found in breast, gastric, prostate, or lung cancer." (PMID 37182141, 2023).
brain malformations (3 papers, 2016 to 2021). "Additionally, a recent study identified three probands with brain malformations and de novo missense variants in ARF1, encoding a small GTP-binding protein." (PMID 30500825, 2018).
breast tumors (3 papers, 2015 to 2025). "We report that ARF1 is highly expressed in breast tumors of the most aggressive and advanced subtypes." (PMID 26908458, 2016).
Chlamydia infection (3 papers, 2011 to 2021). "Although Arf1 localizes to the inclusion and has recently been implicated in Chlamydia infection, the specific roles of Arf1 and its cis- and trans-Golgi-specific GEFS in inclusion biogenesis and/or acquisition of SM has not been previously investigated." (PMID 21909260, 2011). "InaC is required to activate both ARF1 and RhoA, which is tightly regulated during Chlamydia infection." (PMID 34903051, 2021). "Altogether, these data suggest that CT813 uses ARF1 and ARF4 to control Golgi complex positioning during Chlamydia infection." (PMID 28465429, 2017). "Our observation that CT813, ARF1, and ARF4 are key players in Golgi complex positioning thus raised the possibility that they are involved in the manipulation of MTs during Chlamydia infection." (PMID 28465429, 2017). "Next, we used siRNA to test whether ARF1 and ARF4 are also required for Golgi complex positioning during WT Chlamydia infection." (PMID 28465429, 2017). "Since CT813 recruits ARF1 to the inclusion membrane and the nucleotide-bound state of ARF controls its activity, we determined the activation state of ARF during Chlamydia infection." (PMID 28465429, 2017).
colon carcinoma (3 papers, 2020 to 2023). "According to previous works, we first detected the inhibitory effect of rabeprazole on the activity level of ARF1 in CT26 cells (colon carcinoma cells) using a G-LISA assay." (PMID 37452028, 2023). "For example, BFA, the first identified Arf1 inhibitor, was a potent inducer of apoptosis in human leukemia cells or colon carcinoma cells, when used at the concentration of 1 μM." (PMID 31991585, 2020).
gastric cancer (3 papers, 2018 to 2024). A primary or metastatic malignant neoplasm involving the stomach. "We previously demonstrated that targeting the Golgi apparatus using an Arf1 inhibitor, M-COPA, exerted a selective antitumor effect on gastric cancers amplifying the RTK genes MET and FGFR2 by downregulating the cell surface expression of such RTKs." (PMID 29416720, 2018).
hepatocellular carcinoma (3 papers, 2020 to 2023). A malignant tumor that arises from hepatocytes. "We aimed to characterize the roles of small GTPase activators of mTOR including RagC, Rab1A, Rab5, and Arf1 in senescence-like hepatoma cell line HepG2." (PMID 36267578, 2022). "The expression of Arf1 has been reported to be upregulated in multiple cancers, such as breast, prostate, colorectal, gastric, ovarian, or hepatocellular cancers or osteosarcoma." (PMID 31991585, 2020).
liver cancer (3 papers, 2020 to 2024). An epithelial or non-epithelial malignant neoplasm that arises from the liver. "We also observed enhanced mRNA levels of these downstream target genes of the PPARγ signaling in the MYC-ON mouse liver cancer treated with Arf1 inhibitors." (PMID 39872623, 2023). "We first tested human liver cancer Huh-7 cells treated with the Arf1 inhibitor GCA." (PMID 31924786, 2020). "With treatment of the Arf1 inhibitors, we observed increased CCL5 levels in the serum of mice bearing CT26 tumor and upregulated mRNA level of CCL5 in MYC-ON mouse liver cancer." (PMID 39872623, 2023).
pancreatic cancer (3 papers, 2019 to 2024). "The results of qRT-PCR showed relatively elevated mRNA level of ARF1 in pancreatic cancer cell lines (SW1990, HPAC, PaCa-2, CFPAC-1, CAPAN-1), compared with H6C7 cells." (PMID 33345740, 2021). "In our study, qRT-PCR results implied much increased mRNA expression of ARF1 in pancreatic cancer cell lines (SW1990, HPAC, PaCa-2, CFPAC-1, CAPAN-1), compared with H6C7 cells." (PMID 33345740, 2021). "In summary, our study elucidated that downregulation of LINC00460 inhibited the proliferation, migration and invasion, and promoted the apoptosis of pancreatic cancer cells via modulation of miR-320b/ARF1 axis." (PMID 33345740, 2021). "In pancreatic cancer cell lines, PKD2 is known to regulate the secretion of MMP-2, MMP-7 and MMP-9 via a multiprotein complex with ARF1 and ARL1, and Arfaptin2,28,76 aiding the invasion of cells in vitro and in vivo." (PMID 38323010, 2024). "The intracellular C-terminus of ephrin-B1, that is required for invasion of pancreatic cancer cells in vitro and in vivo in mice, was shown to regulate the release of MMP8 from these cells via activation of the cell trafficking regulator, Arf1." (PMID 31514474, 2019).
Salmonella Infections (3 papers, 2015 to 2025). Infections with bacteria of the genus SALMONELLA. "Our pull-down and ELISA data demonstrated that activated ARF1 enhances PIP2 levels on the peroxisomes during Salmonella infection." (PMID 39695325, 2025). "This shows that ARNO was still required to recruit Arf1-FC to the plasma membrane as previously shown for Arf1-WT during Salmonella infection." (PMID 25670778, 2015). "We show that levels of activated ARF1 on isolated peroxisomes increased after Salmonella infection." (PMID 39695325, 2025).
viral infection (3 papers, 2023 to 2025). "Wild-type (WT) OsARF1C overexpression also diminished RNA and reporter protein levels of the RSMV MR, suggesting a potential role for ARF1 in viral disease resistance." (PMID 40834074, 2025). "Improper termination of cGAS-STING triggering in the presence of ARF1 R99C, e.g. after exogenous triggers like viral infection, might accelerate and aggravate disease progression." (PMID 37914730, 2023).
Cerebral ischemia (2 papers, 2025). Restriction of arterial blood supply to the brain associated with insufficient oxygenation to support the metabolic requirements of the tissue. "By lowering lactate production and ADP-ribosylation factor 1 (ARF1) Kla, astrocyte LRP1 facilitates mitochondrial transport from astrocytes to neurons and ameliorates cerebral ischemia and reperfusion injury." (PMID 40149815, 2025).
cervical cancer (2 papers, 2021 to 2025). A primary or metastatic malignant neoplasm involving the cervix. "Using this signature, the patients were divided into Cluster A and Cluster B. Compared with Cluster A, most cuproptosis genes (such as CCDC22, PDHA1, ARF1, and AQP1) in Cluster B were highly expressed, resulting in a better prognosis for patients with cervical cancer." (PMID 41142609, 2025).
ischemic stroke (2 papers, 2024 to 2025). A stroke disorder caused by obstruction of blood flow to the brain, due to thrombotic (local blood clot formation) or embolic (due to a blood clot or other material traveling from another site) event. "This could provide further clarification regarding the inhibitory effect of LRP1 in astrocytes on lactate production and the reduction in ADP-ribosylation factor 1 (ARF1) lactylation, as well as the promotion of astrocyte mitochondrial transfer to neurons and the alleviation of ischemic stroke." (PMID 39683818, 2024).
non-small cell lung carcinoma (2 papers, 2020). A group of at least three distinct histological types of lung cancer, including non-small cell squamous cell carcinoma, adenocarcinoma, and large cell carcinoma. "Notably, Arf1 has been reported to be critical for cell invasion and metastasis in various cancers, including HNSCC, as well as the Arf1 inhibitor AMF-26 helped overcome the acquired resistance to EGFR tyrosine kinase inhibitors in non-small cell lung cancer." (PMID 31991585, 2020).
osteosarcoma (2 papers, 2019 to 2020). A usually aggressive malignant bone-forming mesenchymal neoplasm, predominantly affecting adolescents and young adults. "Amongst them, the discovery of ARF1 is of great significance for improving the diagnosis of osteosarcoma." (PMID 30936265, 2019). "And there were 38 endogenous genes (including ARF1, HSP90AB1, and TUBA1B), 53 TFs (including E2F1, NFKB1, and EGR1), and 858 ncRNAs (including MALAT1, miR-590-3p, and TUG1) were considered as key regulators of osteosarcoma through a series of function enrichment analysis and network analysis." (PMID 30936265, 2019).
poliovirus infection (2 papers, 2013 to 2014). An disease or disorder caused by infection with Enterovirus C. "Arf1, Arf3, and Arf5 were reported to be activated upon poliovirus infection." (PMID 24911624, 2014).
(SARS-CoV) infection (1 paper, 2022). "In response to the severe acute respiratory syndrome-associated coronavirus (SARS-CoV) infection, overexpression of ARF1 can restore Golgi morphology." (PMID 36091067, 2022).
allergic rhinitis (1 paper, 2021). Inflammation of the nasal mucous membranes caused by an IgE-mediated response to external allergens. "Our study also revealed that ARF1 is the direct target of azelastine, a phthalazinone derivative, which is an effective drug in treating allergic rhinitis 45, but its effect on cancer has not been reported." (PMID 33408784, 2021).
anemia (1 paper, 2024). A reduction in the number of red blood cells, the amount of hemoglobin, and/or the volume of packed red blood cells. "A second cluster involved multiple markers of anemia (transferrin and serum iron), strongly associated with markers of one-carbon metabolism (B12, folate), liver metabolism (GGT, ALT, AST, LDH), ADP-ribosylation factors 1 and 3 (ARF1, ARF3), and the structural protein desmatin (DMTN)." (PMID 38543504, 2024).
autoimmune disease (1 paper, 2023). A disorder resulting from loss of function or tissue destruction of an organ or multiple organs, arising from humoral or cellular immune responses of the individual to their own tissue constituents. "ARF1 plays a fundamental role in autoimmune disease development, presumably by inhibiting apoptosis in activated immune cells." (PMID 38200810, 2023).
brain infarction (1 paper, 2025). Tissue necrosis in any area of the brain, including the cerebral hemispheres, the cerebellum, and the brain stem. "This knockdown also induces lactylation at the K73 site in ADP-ribosylation factor 1 (ARF1), which affects vesicle assembly and induces mitochondrial loading abnormalities, thereby blocking the release of mitochondria from astrocytes, ultimately exacerbating the extent of brain infarction in mice." (PMID 40307243, 2025).
Chlamydia (1 paper, 2023). "PI4KIIα was also shown to be important in Chlamydia species bacterial infection by mediating replication complex formation through ADP-ribosylation factor 1 (Arf-1) binding." (PMID 37408244, 2023).
cytomegalovirus infection (1 paper, 2022). A herpesvirus infection caused by Cytomegalovirus. "ARF GTPases are required for different steps of cytomegalovirus infection, and the knockdown of ARF1 can abolish the establishment of cytomegalovirus infection." (PMID 36091067, 2022).
diabetes (1 paper, 2023). "Of the 15 top candidate genes, ST3GAL2, AASS, ARF1 and the transcription factor SIN3A are novel candidates for predicting a refined diabetes risk and intervention response." (PMID 36790478, 2023).
endometrial cancer (1 paper, 2022). Primary or metastatic malignant neoplasm involving the endometrium (mucous membrane that lines the endometrial cavity). "In the case of the ADP-ribosylation factor (ARF)/ARF-like protein (ARL) family, it was observed that a high expression of ARL4D, ARL1, ARF1, and SAR1B in endometrial cancer is associated with better prognosis, while a high expression of ARL4C, ARL2, ARL10, ARL16, and ARL14 promotes worse survival." (PMID 35163161, 2022).
focal epilepsy (1 paper, 2025). A seizure caused by a localized disorder. "This study presents the initial case of ARF1‐related disease in China, featuring drug‐refractory and focal epilepsy as well as mild growth delay in comparison to peers." (PMID 40689678, 2025).
gram-positive bacterial infections (1 paper, 2017). Infections caused by bacteria that retain the crystal violet stain (positive) when treated by the gram-staining method. "Thus the increased production of the Toll pathway AMP Drosomycin in the absence of ARF1 or Asrij does not protect lifespan upon Gram positive bacterial infection." (PMID 28273919, 2017).
Impaired glucose tolerance (1 paper, 2026). An abnormal resistance to glucose, i.e., a reduction in the ability to maintain glucose levels in the blood stream within normal limits following oral or intravenous administration of glucose. "Proteomic analysis revealed that individuals with impaired glucose tolerance (IGT) had reductions in proteins regulating glycolysis (PGK1, G3P), lipid metabolism (ACBP, ARF1), glucose transport (14-3-3B), and insulin secretion (STARD10, CAPDS) compared with normal glucose-tolerant (NGT) individuals." (PMID 41854718, 2026).
malignant lymphoma (1 paper, 2020). "In addition to the effects depending on myristoylated SFKs, HGAL, and Arf1 proteins, given that there are hundreds of known myristoylated proteins, PCLX-001-mediated effects on lymphoma cell viability likely also occur via the loss of functionality of other myristoylated proteins." (PMID 33093447, 2020). "This newly described N-degron system may therefore contribute to the faster degradation of unmyristoylated proteins seen in malignant lymphoma cell lines treated with PCLX-001 such as SFKs, HGAL, and Arf1." (PMID 33093447, 2020).